LEP (leptin)
Diseases named in the same sentence as LEP in open-access papers (continued):
Sharing a sentence is not in itself a finding about the gene and the disease.
gestational diabetes (101 papers, 2007 to 2026). Carbohydrate intolerance first diagnosed during pregnancy. "Disrupted leptin signaling has been associated with recurrent miscarriage, pre-eclampsia, gestational diabetes, and intrauterine growth restriction." (PMID 41341138, 2025). "Maternal gestational diabetes (GDM) positively associated with cord blood leptin concentrations but inversely associated with cord blood adiponectin concentrations." (PMID 34864815, 2022). "Leptin, along with its receptor, are linked with mechanisms affecting a diverse array of pregnancy-specific pathologies that include gestational diabetes and intrauterine growth restriction." (PMID 36128550, 2022). "During pregnancy, higher levels of leptin in the first and second trimesters have been associated with the development of gestational diabetes, whereas regular physical activity during pregnancy has been associated with a beneficial decrease of leptin levels." (PMID 34948770, 2021). "High leptin levels in the first and second trimesters of pregnancy have been associated with the development of gestational diabetes; thus, these findings emphasise the importance of healthy lifestyle behaviour before and during pregnancy." (PMID 34948770, 2021). "We assessed the association between first trimester leptin, resistin, visfatin, BMI and maternal characteristics and the development of gestational diabetes mellitus in the Ho municipality." (PMID 31836012, 2019). "Too high leptin levels are also associated with gestational diabetes and macrosomia." (PMID 39479521, 2024). "Furthermore, this study found adiponectin, leptin, resistin and visfatin levels to be significantly associated with gestational diabetes." (PMID 38597653, 2024). "The expression of leptin and its receptor is increased in the placentas from women with gestational diabetes, activating protein synthesis and therefore partly explaining the increased foetal growth associated with gestational diabetes." (PMID 34523036, 2022). "A recent study suggests that high preconceptual leptin levels may be a body mass index-independent risk factor for gestational diabetes mellitus and also a body mass index-dependent risk factor for hypertensive pregnant women." (PMID 36034841, 2022). "The increased level of placental leptin has been linked to several metabolic conditions during pregnancy, such as maternal obesity and gestational diabetes mellitus (GDM)." (PMID 37497352, 2023). "Log cord serum leptin were independently associated BW, BL, and HC in the multivariable regression analysis, after adjustment for gestational age, delivery mode, multiple gestation, pregnancy induced hypertension, gestational diabetes mellitus, infant’s BMI, and log cord serum IGF-1." (PMID 32607107, 2020). "Elevated baseline serum leptin levels have been reported in pregnant women diagnosed with gestational diabetes mellitus (GDM)." (PMID 40565847, 2025). "Leptin appears to be a relevant key hormone that regulates placental transport, and this regulation is altered in pathophysiological conditions such as gestational diabetes." (PMID 37497352, 2023). "Free leptin index (leptin/SLR) was lower in SF than in CGMP-RW at four months when data were adjusted for gestational diabetes mellitus, weight gain during pregnancy, smoking, and maternal and paternal BMI." (PMID 36839368, 2023). "The insulin resistance of pregnancy is exacerbated by maternal obesity, excessive gestational weight gain, and gestational diabetes, resulting in even lower maternal levels of adiponectin and higher levels of insulin, leptin, and IGF-1." (PMID 37764824, 2023). "Cord blood leptin and leptin per kg of infant weight are higher in newborns of mothers with gestational diabetes compared to normal pregnancies." (PMID 37764824, 2023). "Gestational diabetes mellitus (GDM) “programs” an elevated risk of metabolic dysfunctional disorders in the offspring, and has been associated with elevated leptin and decreased adiponectin levels in cord blood." (PMID 37020805, 2023).
gestational diabetes (continued). "Several cytokines including leptin were associated with maternal body weight (coeff 0.9; p = 2.31 × 10−5), smoking habits (i.e., ICAM-1 coeff 133.3; p = 0.09), or gestational diabetes (i.e., ICAM-1 coeff 688; p = 0.06)." (PMID 37299395, 2023). "Related findings include differential methylation in cord blood in genes ATP5A1, MFAP4, PRKCH, SLC17A4 related to Gestational Diabetes (GDM); and hypermethylation of the LEP gene promoter associated with maternal obesity on the fetal side of the placenta." (PMID 35749371, 2022). "Yamashita H., Shao J., Ishizuka T., Klepcyk P.J., Muhlenkamp P.,Qiao L., Hoggard N., Friedman J.E. Leptin administration preventsspontaneous gestational diabetes in heterozygous Lepr(db/+) mice:effects on placental leptin and fetal growth." (PMID 34782887, 2021). "Logarithmic transformed mean concentrations and standard deviation (SD) and logistic regression analysis of sFRP4, Chemerin, Leptin and Adiponectin concentrations in gestational diabetes (GDM) and uncomplicated (control) pregnancies." (PMID 33206702, 2020). "Model II was designed to assess the interactions between GWG, maternal obesity, gestational diabetes, and sex of the neonate regarding their effect on birthweight, skinfolds, and leptin." (PMID 33182482, 2020). "In an attempt to further understand the pathophysiology of this increase in neonatal fat mass, we aimed to analyze the relative contribution of GWG, maternal obesity, and gestational diabetes in proxies of neonatal fat mass, i.e., skinfolds and cord leptin." (PMID 33182482, 2020). "We previously conducted a prospective exposure-matched cohort study to determine the relative contribution of maternal obesity and gestational diabetes on neonatal birthweight and fat mass, estimated by skinfold sum and cord serum leptin." (PMID 33182482, 2020). "Leptin is emerging as a key component in obese pregnancy-related pathologies such as gestational diabetes mellitus, and macrosomia." (PMID 31540056, 2019). "There were also significant positive correlations between leptin, resistin, and visfatin and gestational diabetes mellitus." (PMID 31836012, 2019). "First, placental oxidative stress and mitochondrial dysfunction was observed in maternal obesity coincided with gestational diabetes and correlated with neonatal leptin levels." (PMID 30103773, 2018). "Furthermore, deregulation of leptin levels has been correlated with the pathogenesis of various disorders associated with reproduction and gestation, including polycystic ovary syndrome, recurrent miscarriage, gestational diabetes mellitus, pre‐eclampsia and intrauterine growth restriction." (PMID 29160594, 2018). "Neonatal leptin levels are higher when gestational diabetes mellitus occurred during pregnancy and when mothers had a higher BMI." (PMID 30103773, 2018). "The crude prevalence of GDM in the metropolis was 8.0%.The plasma level of the placenta peptides, Leptin, Progesterone and Estradiol estimated were increased in the women who developed gestational diabetes mellitus." (PMID 28732072, 2017). "Recent data suggest that the dysregulation of leptin, adiponectin, and kisspeptin during pregnancy contributes to gestational diabetes mellitus and pre-eclampsia." (PMID 28409493, 2017). "Yet, in the first months, decreased cord leptin levels together with gestational diabetes mellitus are related to a slower weight gain." (PMID 27440187, 2016). "In human IUGR, maternal serum concentrations of IGF-I, insulin, and leptin are decreased while obese pregnant women and pregnancies complicated with gestational diabetes have higher serum levels of leptin, insulin, IGF-I, and decreased levels of adiponectin." (PMID 26858656, 2016).
gestational diabetes (continued). "The results showed that in women with gestational diabetes, there was a strong correlation between the appreciation of 10% sucrose-flavored milk and the level of fasting serum leptin, as well as a strong correlation between the average sweet taste of sweet solutions and fasting serum insulin level." (PMID 40806099, 2025). "Moreover, one study each reported adiponectin, leptin, resistin and visfatin levels were significant predictors of gestational diabetes." (PMID 38597653, 2024). "According to Bozkurt and coworkers, adiponectin and leptin plasma levels reflect deteriorated glucose metabolism at early gestation and may predict gestational diabetes mellitus (GDM)." (PMID 38612666, 2024). "However, unchanged and decreased levels of leptin have been reported in patients with gestational diabetes." (PMID 37964253, 2023). "Gestational diabetes-related immune dysregulation has been shown to lead to increased maternal IL-6 with enhanced placental leptin production but a paradoxical reduction in the IL-6 levels of the LGA offspring, possibly related to the hyperleptinemia that is typically seen in LGA infants." (PMID 35197933, 2022). "However, the majority of studies investigating the leptin and adiponectin systems in the human placenta were performed in women with gestational diabetes." (PMID 33801130, 2021). "In contrast, the effect of first and third trimester weight gain on the increase in cord leptin level was significantly higher in newborns whose mothers had gestational diabetes (respectively for one-kilogram weight gain, +0.47 ng/mL, p = 0.038 and +0.89 ng/mL, p = 0.005)." (PMID 33182482, 2020). "The aim of this study was to evaluate whether soluble frizzled-related protein 4 (sFRP4) concentration in the first trimester of pregnancy is individually, or in combination with Leptin, Chemerin and/or Adiponectin, associated with the development of gestational diabetes (GDM)." (PMID 33206702, 2020). "In addition, leptin seems to facilitate nutrients transport to the fetus in gestational diabetes by increasing the expression of the glycerol transporter aquaporin-9." (PMID 32630697, 2020). "The Fit for Delivery intervention in low risk women showed a reduction in insulin and leptin concentrations, but this did not reduce the incidence of gestational diabetes, the primary outcome." (PMID 31601214, 2019). "However, in those with gestational diabetes, 2-hour postload glucose was inversely correlated with fetal-side placental tissue DNA methylation of the leptin gene, but positively correlated with this in maternal-side tissue." (PMID 24664798, 2014). "Mixed-effects model analysis was used to assess the differences in adiponectin and leptin between groups, after adjustment for time, maternal age, ethnic group, parity, method of conception, BMI, smoking, gestational age at measurement and development of gestational diabetes mellitus." (PMID 42240794, 2026). "Similarly, among pregnant women with or without gestational diabetes, cord blood leptin levels rise in association with increasing maternal fasting blood sugar levels." (PMID 37764824, 2023). "Furthermore, it was reported that maternal obesity (no concomitant gestational diabetes) was linked to the increased DNA methylation of the leptin promoter only in the fetus and to adiponectin promoter hypomethylation." (PMID 33801130, 2021). "Again, circulating leptin level in healthy pregnant women is higher than that in non-pregnant females (leptin concentration in healthy adult women is reported around 21.9 ng/mL;), but maternal leptin levels are even higher in women with gestational diabetes mellitus." (PMID 33114326, 2020). "Moreover, increased levels of both A-FABP and leptin has been shown in gestational diabetes mellitus, suggesting that A-FABP might be a contributor to the increased metabolic and cardiovascular risk of the disease." (PMID 32753620, 2020).
gestational diabetes (continued). "Similarly, log cord serum IGF-1 were independently associated with BW and BL in the multivariable regression analysis, after adjusting for gestational age, delivery mode, multiple gestation, pregnancy induced hypertension, gestational diabetes, infant’ BMI, and log cord serum leptin." (PMID 32607107, 2020). "Moreover, increased leptin levels are found in the most frequent pathology of pregnancy: gestational diabetes, where leptin may mediate the increased size of the placenta and the fetus, which becomes macrosomic." (PMID 32630697, 2020). "This may explain our observation that third trimester GWG was associated with an increase in leptin level, but not skinfold thickness, in cases of gestational diabetes." (PMID 33182482, 2020). "Lipids and adipokines including leptin, resistin and visfatin play various roles in the pathophysiology of Gestational Diabetes Mellitus (GDM)." (PMID 31836012, 2019). "Furthermore, dysfunctions of leptin metabolism or regulation in the placental unit and plasma are enhanced in pregnancies complicated with various abnormalities such as intrauterine growth restriction, gestational diabetes mellitus, and PE." (PMID 29379664, 2017). "Hence, leptin, as a pro-inflammatory factor, may contribute to the inflammatory state during gestational diabetes." (PMID 22144985, 2011). "In particular, other adipokines, such as leptin, visfatin, and adiponectin, are dysregulated in gestational diabetes (GDM) and they may have a pathological significance and prognostic value in this pregnancy disorder." (PMID 41497562, 2025). "Potential involvemehasof hsa-miR-875-5p to regulate TNF, LEP and IRS1 genes in gestational diabetes mellitus was demonstrated in a recent study." (PMID 33670024, 2021). "We collected maternal and neonatal anthropometric data (n = 49) in normoglycemic healthy lean, obese or obese with gestational diabetes mellitus women, as well as determined UCB leptin and insulin concentrations by ELISA." (PMID 27440187, 2016). "A negative relationship has been reported between plasma leptin and VO2peak/kg and VO2peak in women with gestational diabetes." (PMID 37964253, 2023). "This study reveals potential molecular mechanisms underlying gestational diabetes mellitus (GDM), including changes in the gut microbiota, abundance and composition of intestinal microbiota, and overexpression of leptin protein, which may affect the development of GDM." (PMID 37684563, 2023). "Mothers with gestational diabetes have higher levels of TNF-alpha, leptin and visfatin and lower levels of adiponectin that, in turn, might have a significant impact on the development of the immune response in infancy." (PMID 34682108, 2021). "Leptin, progesterone, estradiol estimated in this study were increased in the gestational diabetes mellitus women and fairly predicted gestational diabetes in the non-diabetics pregnant women." (PMID 28732072, 2017). "We studied adipokine plasma levels, SAT gene expression, and DNA methylation of LEP, ADIPOQ, and RETN in adult offspring of women with gestational diabetes (O-GDM, N = 82) or type 1 diabetes (O-T1DM, N = 67) in pregnancy, compared to offspring of women from the background population (O-BP, N = 57)." (PMID 28413567, 2017). "The role of leptin, adiponectin, ghrelin, resistin, and IGF-I as appetite regulation molecules is well established, but there have been no general conclusions on their levels in human milk, especially in regard to the occurrence of maternal gestational diabetes." (PMID 38612666, 2024). "However, no more than 155 children were included in these analyses: the possible mediating effects by gestational diabetes, inflammatory cytokines and leptin cannot be completely ruled out." (PMID 32557131, 2020). "However, UCB leptin levels did not correlate with UCB insulin levels in the offspring of obese women with gestational diabetes mellitus." (PMID 27440187, 2016).
gestational diabetes (continued). "This study aimed to compare the plasma glucose concentrations and serum insulin, leptin and adiponectin in cord blood of babies of women (a) without gestational diabetes mellitus (GDM), (b) with mild GDM under routine care, or (c) mild GDM with treatment." (PMID 17430602, 2007). "Adipose tissue-derived cytokines, such as leptin and TNF-α, may impair placental nutrient transport and fetal β-cell development, thereby creating a pro-macrosomic milieu independent of gestational diabetes mellitus (GDM)." (PMID 40655485, 2025).